SETD3 (SET domain containing 3, actin N3(tau)-histidine methyltransferase)
Description:
Protein-histidine N-methyltransferase that specifically mediates 3-methylhistidine (tele-methylhistidine) methylation of actin at 'His-73'. Histidine methylation of actin is required for smooth muscle contraction of the laboring uterus during delivery. Does not have protein-lysine N-methyltransferase activity and probably only catalyzes histidine methylation of actin.
Synonyms: hSETD3; C14orf154; FLJ23027
Tractability: Small molecule: a structure with a bound ligand is known; it has a high-quality binding pocket. PROTAC: UniProt records ubiquitination sites on it; ubiquitination databases record sites on it; its protein half-life has been measured.
Safety:
Unwanted effects reported when the protein is acted on. In parentheses: how it was acted on, where the effect was seen, and who reports it.
neutropenia (source: ClinPGx)
Gene: Protein-coding gene on chromosome 14 (99,395,061 to 99,480,927, reverse strand). Ensembl gene ENSG00000183576.
Subcellular location: Cytoplasm; Nucleus
Subcellular location (Human Protein Atlas): Mitochondria
Pathways (Reactome):
Chromatin organization: PKMTs methylate histone lysines
Gene Ontology:
Molecular function: protein binding; protein-L-histidine N-tele-methyltransferase activity; protein-lysine N-methyltransferase activity; histone H3K36 methyltransferase activity; histone H3K4 methyltransferase activity; transcription coactivator activity; RNA polymerase II-specific DNA-binding transcription factor binding
Biological process: actin filament organization; positive regulation of DNA-templated transcription; positive regulation of transcription by RNA polymerase II; regulation of uterine smooth muscle contraction; chromatin remodeling
Cellular component: cytoplasm; nucleus; nucleoplasm; chromatin
Genetic constraint (gnomAD): Loss-of-function variants: 17 observed, 53.33 expected, observed/expected ratio (o/e) 0.32, 90% interval 0.22 to 0.48. The upper end of that interval is the gene's LOEUF score, 0.48, which puts it in group 2 of 6, group 1 being the genes least tolerant of losing a copy. Missense variants: 534 observed, 687.75 expected, observed/expected ratio (o/e) 0.78, 90% interval 0.72 to 0.83. Synonymous variants: 261 observed, 251.8 expected, observed/expected ratio (o/e) 1.04, 90% interval 0.94 to 1.15.
Homologues: Orthologues: chimpanzee SETD3 (99% identical), macaque SETD3 (99% identical), rat Setd3 (92% identical), mouse Setd3 (92% identical), dog SETD3 (90% identical), guinea pig SETD3 (88% identical), pig SETD3 (88% identical), rabbit SETD3 (82% identical), tropical clawed frog setd3 (77% identical), zebrafish setd3 (71% identical), Drosophila melanogaster Setd3 (30% identical), Caenorhabditis elegans set-27 (25% identical). Paralogues in human: SETD6 (19% identical), SETD4 (14% identical).
Diseases named in the same sentence as SETD3 in open-access papers:
SETD3 is named in the same sentence as 31 diseases in open-access papers, as found by Europe PMC text mining. Sharing a sentence is not in itself a finding about the gene and the disease. The quoted sentences say what the papers report.
hepatocellular carcinoma (9 papers, 2018 to 2024). A malignant tumor that arises from hepatocytes. "circ_0000567 is an ecircRNA spliced from SETD3 and has already been demonstrated to be a potential diagnostic biomarker in colorectal cancer; it has also been found to sponge miR-421 to inhibit hepatocellular carcinoma (HCC) growth." (PMID 35371319, 2022). "SETD3-positivity has been reported to be associated with poor prognosis in hepatocellular carcinoma." (PMID 32133296, 2020). "As expected, the knockdown of Plk1 alleviated severe liver carcinoma caused by Setd3." (PMID 35912180, 2022). "Correlation analysis indicated that upregulated SETD3 was positively correlated with higher levels of PLK1 in hepatocellular carcinoma samples (R = 0.4847, p = 0.021)." (PMID 35912180, 2022). "Upregulation of USP27 in hepatocellular carcinoma patients leads to elevated SETD3 expression and increased cell proliferation, invasion, migration and tumorigenesis." (PMID 35018513, 2022). "Circ_0000567, which is originated from SETD3, inhibits the growth of hepatocellular carcinoma via serving as a ceRNA of MAPK14 through sponging miR-421." (PMID 32493490, 2020). "In addition, we found that USP27 and SETD3 expression are positively correlated in human hepatocellular carcinoma (HCC), and tumor patients with lower expression levels of SETD3 and USP27 have a longer five-year survival." (PMID 35018513, 2022). "Therefore, our data suggest that elevated SETD3 induces hepatocellular carcinoma by enhancing PLK1 expression." (PMID 35912180, 2022). "Inhibition of USP27 expression led to the downregulation of SETD3 protein level, the blockade of the cell proliferation and tumorigenesis of hepatocellular carcinoma (HCC) cells." (PMID 35018513, 2022). "Similar to RCTs, SETD3 protein levels were also found to be elevated in hepatocellular carcinoma (HCC) and even positively correlate with increasing stages of liver cancers." (PMID 30067821, 2018). "Indeed, the level of SETD3 was shown to be elevated in hepatocellular carcinoma (HCC)." (PMID 34685411, 2021).
breast carcinoma (8 papers, 2019 to 2024). "Our investigation suggests that high tumoral levels of SETD3 are associated with a better outcome of breast cancer patients especially in ER-positive tumors." (PMID 32042016, 2020). "Then, we employed SETD3 siRNA knockdown in vitro in a range of well-established human mammary carcinoma cell lines to analyze the role of SETD3 depletion in cytoskeleton-associated functions with relevance to malignant cell behavior." (PMID 32042016, 2020). "We can also conclude that the function of SETD3 depends on the presence of mutations and the expression patterns of other genes in breast cancer." (PMID 32042016, 2020). "However, in those with estrogen receptor-positive and or luminal A-type breast cancer, SETD3 has been linked with increased relapse-free survival rates." (PMID 39765675, 2024). "In addition, SETD3 regulates the expression of multiple breast-cancer-associated genes, such as ACTB, FBXW7, Fascin, eNOS, and MMP-2, which suggests it as a promising biomarker for breast cancer prognosis." (PMID 35912180, 2022). "However, in cancers associated with women, we observed higher expression of SETD3 in breast cancer compared to cervical, endometrial and ovarian cancer." (PMID 32042016, 2020). "The protein levels of SETD3 were upregulated in breast cancer tissues compared with those in normal breast tissue." (PMID 38272222, 2024). "To evaluate the clinical significance of SETD3 in breast cancer, we first analyzed the protein levels of SETD3 using the Clinical Proteomic Tumor Analysis Consortium (CPTAC)." (PMID 38272222, 2024). "By contrast, in patients with estrogen receptor positive breast cancer, a higher level of SETD3 correlated with better clinical outcomes." (PMID 34685411, 2021). "In this study, we first analyzed the prognostic value of SETD3 in breast cancer patients using the database of the public Kaplan-Meier plotter." (PMID 32042016, 2020). "Overall, these results demonstrate a role for SETD3 in cytoskeletal organization and function of aggressive breast cancer cells, which correlates with our observation that the expression of SETD3 in triple negative tumors was related to poor prognosis." (PMID 32042016, 2020). "In summary, our results suggest that the expression of SETD3 influences the survival of breast cancer patients." (PMID 32042016, 2020). "Our study suggests that SETD3 expression can act as a subtype-specific biomarker for breast cancer progression and prognosis." (PMID 32042016, 2020). "For example, it has been reported that SETD3 negatively correlates with prognosis in breast cancers." (PMID 33339442, 2020). "As a prerequisite for studying SETD3 function in vitro, we characterized its expression by quantitative real-time PCR (qPCR) in a panel of seven representative human mammary cancer cell lines." (PMID 32042016, 2020). "Next, we explored whether SETD3 plays oncogenic roles in breast cancer, and an EdU incorporation assay and FUCCI system were utilized." (PMID 38272222, 2024). "The inhibition of SETD3 expression blocks the viability and invasiveness of breast cancer cells." (PMID 35018513, 2022).
breast carcinoma (continued). "We observed that the high expression of SETD3 was associated with better relapse-free survival (RFS) of the whole collective of 3,951 patients, of Estrogen Receptor-positive, and of Luminal A-type breast cancer patients." (PMID 32042016, 2020). "In breast cancer, however, our study indicates a bivalent role of SETD3." (PMID 32042016, 2020). "In order to establish whether SETD3 expression could have an impact on breast cancer prognosis, we investigated its relation to relapse-free survival (RFS)." (PMID 32042016, 2020). "Based on this evidence, we hypothesize that alterations in SETD3 expression may affect cytoskeletal function, cancer cell motility and clinical outcome in breast cancer patients." (PMID 32042016, 2020). "However, there is little knowledge about the role of SETD3 in the progression and prognosis of breast cancer." (PMID 32042016, 2020). "Moreover, in vitro assays were performed to assess the role of SETD3 in the viability and capacity of invasion of human breast cancer cell lines." (PMID 32042016, 2020). "Finally, we observed that SETD3 regulates the invasive potential and the cytoskeleton of highly aggressive mammary cancer cells." (PMID 32042016, 2020). "Therefore, we sought to investigate whether NUDT16-mediated dePARylation of SETD3 contributes to the regulation of replication stress resolution and radioresistance in breast cancer cells, and a comet assay was performed." (PMID 38272222, 2024).
liver cancer (8 papers, 2018 to 2024). An epithelial or non-epithelial malignant neoplasm that arises from the liver. "Taken together, these data revealed that knockdown of USP27 or SETD3 prevents liver cancer cell migration and invasion." (PMID 35018513, 2022). "A study reported in 2017 has validated the potential mechanism of a E3 ligase SCFFBXW7 by ubiquitinating SETD3 to regulate the liver cancer progression." (PMID 35018513, 2022). "Overexpression of SETD3 in liver cancer cells promotes cell proliferation and tumorigenesis and SETD3 protein levels correlate with high malignancy and poor prognosis in liver tumors." (PMID 30150556, 2018). "Notably, GSK3β-mediated phosphorylation of SETD3 is a prerequisite for FBXW7β-dependent ubiquitination and protein degradation of SETD3, thereby attenuating its oncogenic role in the proliferation of liver cancer cells." (PMID 38272222, 2024). "Furthermore, another study indicated that SETD3 level is positively correlated with cell proliferation of liver cancer cells and liver tumorigenesis in a xenograft mouse model." (PMID 35018513, 2022). "Furthermore, the overexpression of SETD3 leads to cell proliferation and tumor growth in liver cancer cells." (PMID 33168059, 2020). "Interestingly, in the same study, the expression of SETD3 was higher in specimens of liver cancer patients with grade III22." (PMID 32042016, 2020). "Since SETD3 is overexpressed in Renal cell tumors and SETD3 protein levels correlate positively with the proliferation rate of liver cancer cells, we first asked whether SETD3 regulates cell growth or proliferation in vivo in the animal." (PMID 30067821, 2018). "Particularly, our recent study showed that aberrant elevated SETD3 protein levels were detected in HCC tissues, and xenograft mice model confirmed that SETD3 levels are positively correlated with tumorigenesis, which indicates that SETD3 is an important player in liver cancers." (PMID 35912180, 2022).
cervical cancer (3 papers, 2020 to 2024). A primary or metastatic malignant neoplasm involving the cervix. "Although these studies characterize SETD3 as an oncoprotein, evidence demonstrates that high levels of SETD3 enhance the sensitization of cervical cancer cells to radiotherapy, potentially implicating SETD3 as a tumor suppressor." (PMID 39765675, 2024). "Moreover, SETD3 downregulates the expression of kinesin light chain 4 (KLC4), which could improve the radiosensitivity of cervical cancer cells." (PMID 35912180, 2022).
triple-negative breast carcinoma (3 papers, 2020 to 2024). An invasive breast carcinoma which is negative for expression of estrogen receptor (ER), progesterone receptor (PR), and human epidermal growth factor receptor 2 (HER2). "Some studies show that high expression of the SETD3 gene is associated with poor survival in triple-negative breast cancer, while HOXB3 and FOXA1 were identified as indicators of better prognosis." (PMID 34416858, 2021). "Indeed, SETD3 protein expression was markedly increased in both estrogen receptor (ER) positive and triple-negative breast cancer (TNBC) cells relative to normal breast epithelial MCF10A cells and human epidermal growth factor receptor 2 (HER2) positive SKBR3 cells." (PMID 38272222, 2024).
bladder cancer (2 papers, 2019 to 2022). "As an epigenetic regulator, SETD3 was previously suggested as a crucial oncogenic modulator in bladder cancer." (PMID 35402263, 2022). "Through integrative analysis, we identified six HMT genes (PRDM9,ASH1L,SETD3,SETD5,WHSC1L1, and KMT2D) that may play a key role in the development and progression of bladder cancer." (PMID 30984543, 2019).
colon cancer (2 papers, 2019 to 2020). "Specifically, our work proposes that low levels of SETD3 may serve as a potential diagnostic marker of resistance to DOX treatment in colon cancer patients." (PMID 30683849, 2019). "In the current study, we show that SETD3 is a positive regulator of DNA-damage-induced apoptosis in colon cancer cells." (PMID 30683849, 2019). "We found that high expression of SETD3 correlates with better survival of colon cancer patients which highlights the link between our findings to the clinics." (PMID 30683849, 2019). "Bioinformatics database analysis revealed that high expression of SETD3 correlates with higher survival rate in colon cancer patients." (PMID 30683849, 2019). "To further explore the cellular roles of SETD3 in colon cancer, we immunoprecipitated SETD3 from HCT-116 cells followed by mass spectrometry and identified 215 novel interacting proteins showing a significant link to DNA damage response pathways." (PMID 30683849, 2019). "Finally, Kaplan–Meier survival analysis, of two-independent cohorts of colon cancer patients, revealed that low expression of SETD3 is a reliable predictor of poor survival in these patients, which correlates with our findings." (PMID 30683849, 2019).
colorectal cancer (2 papers, 2019 to 2022). A primary or metastatic malignant neoplasm that affects the colon or rectum. "To study the cellular role of SETD3 in colorectal carcinoma cells (HCT-116), we immunoprecipitated overexpressed FLAG-SETD3 from the nuclear fraction followed by mass spectrometry." (PMID 30683849, 2019).
enteroviral infection (2 papers, 2022 to 2025). "Thus, SETD3 is not required for the CVB3 2Apro-mediated cleavage of eIF4GI during enteroviral infection." (PMID 35891342, 2022).
lung adenocarcinoma (2 papers, 2022 to 2024). A carcinoma that arises from the lung and is characterized by the presence of malignant glandular epithelial cells. "At the same time, we analyzed the mutation rates of H3K36 enzymes (including NSD1, NSD2, NSD3, ASH1L, SMYD2, SETDB2, SETD3, and SETMAR) in lung adenocarcinoma, which showed that the amplification mutation frequency of H3K36 enzymes was at a low level." (PMID 39119928, 2024). "And the results demonstrated that tumor SETD3 expression is significantly positively related to EV-hY4F level in lung adenocarcinoma patients." (PMID 35410432, 2022). "Furtherly, we analyzed the correlation of circulating EV-hY4F and tumor SETD3 expression using plasma and paired tumor tissue samples from lung adenocarcinoma (LUAD) patients." (PMID 35410432, 2022).
lymphoma (2 papers, 2019 to 2020). A malignant (clonal) proliferation of B- lymphocytes or T- lymphocytes which involves the lymph nodes, bone marrow and/or extranodal sites. "Previously, the expression of SETD3 has been associated with oncogenesis of lymphoma and liver cancer." (PMID 32042016, 2020). "In lymphoma, a truncated variant of SETD3 lacking the SET domain sequences is highly expressed in the lymphoma and promotes lymphomagenesis." (PMID 30795787, 2019).
ovarian carcinoma (2 papers, 2020). A malignant neoplasm originating from the surface ovarian epithelium. "The prognostic potential of the CCC-related biomarkers was validated in an external gene expression dataset (KM plotter) for OS of ovarian cancer patients (n = 655 for CCT5, KCTD10, and SETD3; n = 1,656 for the remaining CCC-related biomarkers)." (PMID 32133296, 2020).
viral infection (2 papers, 2021 to 2022). "Simultaneous mutation of three key residues in the SET interaction domain led to a complete loss of SETD3′s ability to support viral infection, even when this mutant (SET257+266+288) was overexpressed to levels much higher than endogenous SETD3." (PMID 36075902, 2022). "In the context of viral infections, the region encoding the SETD3 protein was recently shown to be an integration site in the precancerous human papillomavirus infections." (PMID 34685411, 2021). "Our findings that structure-guided mutations in SETD3 that ablate protein-protein interactions negate viral infection strongly suggest that SETD3′s role in viral replication is mediated solely by virtue of its interaction with the viral nonstructural protein 2A." (PMID 36075902, 2022). "Complementation with either a SETD3 WT or a catalytic dead SETD3 restored viral infection similar to WT levels." (PMID 36075902, 2022). "We next tested which SETD3 residues in the 2A binding interface are critical for viral infection." (PMID 36075902, 2022). "An in vivo study indicated that SETD3 deficient (Setd3−/−) mice were viable and showed no symptoms of viral infection." (PMID 34685411, 2021). "However, we cannot exclude that SETD3 has a subtle effect on the kinetics of 2A protease activity during viral infection, which could be crucial, especially early in the viral life cycle when 2A is limiting." (PMID 36075902, 2022). "While only two reports are currently available regarding the importance of the SETD3 protein in viral contagiousness, it is extremely important, taking into account the current pandemic status, to investigate the role of host proteins in the progression of viral infections." (PMID 34685411, 2021).